ERBB2 (erb-b2 receptor tyrosine kinase 2)
Diseases named in the same sentence as ERBB2 in open-access papers (continued):
Sharing a sentence is not in itself a finding about the gene and the disease.
tumor (continued). "Low PIP4K2B expression associates with increased tumor size and distant metastasis, whereas high PIP4K2B expression strongly associates with ERBB2 expression." (PMID 27895661, 2016). "To mechanistically link the enhanced anti-tumor response of Trast-NG/DOX + 17-AAG combination with the effects of 17-AAG on ErbB2, we performed IHC and Western blot analyses of ErbB2 levels in tumors of mice treated with various regimens." (PMID 26859680, 2016). "ET6 contains only a fraction of the HER2-enriched or ERBB2-amplified tumors (around 20 %), and it is likely that our use of tumor sets containing many HER2-enriched tumors was essential to identifying this HER2-associated epitype." (PMID 26923702, 2016). "Eligibility of BC patients to HER2-targeted therapy depends on detection of HER2/ERBB2 overexpression/amplification in the tumor tissue by immunohistochemistry (IHC) and/or in situ hybridization (ISH)." (PMID 27716627, 2016). "In this review, we present a state-of-the-art on how ErbB2 is regulated in physiological conditions and in tumor cells and how this knowledge translates into smart drug design." (PMID 27596216, 2016). "The altered RTKs in UC have been reported and associated with tumor cell proliferation and survival, including FGFR3 activation, EGFR amplification, ERBB3 mutation, and ERBB2 mutation or amplification." (PMID 27793038, 2016). "ERBB2 expression is statistically significantly correlated with tumor localization (P=0.005), with a higher number of ERBB2-positive cases in the left colon." (PMID 26779809, 2016). "Tumor growth is critically dependent on ErbB2 amplification, a process coined oncogenic addiction of malignancy." (PMID 27596216, 2016). "In vivo, genetic ablation of β2-chimaerin in the MMTV-Neu/ErbB2 mice accelerates tumor onset, but delays tumor progression." (PMID 27058424, 2016). "Here we report that TOM1L1 is co-amplified with ERBB2 and defines a subgroup of HER2+/ER+ tumours with early metastatic relapse." (PMID 26899482, 2016). "Counting of ERBB2 FISH signals in the tumor cells and ERBB2 CN values obtained by MIP showed a particularly tight correlation (rs = 0.940, P < 0.001) and an excellent agreement on a case-by-case basis." (PMID 27716627, 2016). "By forming a complex with ErbB2 or αB-crystallin, 14-3-3ζ promoted tumor metastasis by inducing EMT of tumor cells." (PMID 26910835, 2016). "Our previous data demonstrated that p130Cas is an essential transducer element in ErbB2 transformation and progression showing that p130Cas is necessary for ErbB2-dependent foci formation, anchorage-independent growth, in vivo tumor growth and metastatization." (PMID 26716506, 2016). "ERBB2 plays an important role in cell growth, survival, and differentiation in normal cells, and overexpression of ERBB2 promotes tumor growth, metastasis, and angiogenesis in cancer." (PMID 27203740, 2016). "EphA2 is known to form a complex with ErbB2/HER2/Neu that is important for tumour initiation and metastasis in MMTV-Neu transgenic mice." (PMID 27619642, 2016). "Tumor growth in ErbB2-amplified cells mainly results from the ligand-independent formation of ErbB2/ErbB3 oncogenic complexes." (PMID 27596216, 2016). "In contrast, the sustained inhibition of AKT seems to be the prerequisite for eliciting apoptosis in ErbB2-overexpressing tumours and signifies the importance of preventing the p-AKT rebound for the potency of anti-ErbB2/ErbB3-targeting agents." (PMID 27255951, 2016). "These approaches, based on understanding of the compensatory mechanisms, are aimed at preventing the emergence of resistance in tumours, which show an initial response to blockade of ErbB2." (PMID 27255951, 2016). "By its design, MM-111 blocks the activity of ligand-dependent and ligand-independent ErbB2/ErbB3 complexes in tumor cells, hence, recapitulating the effect of combining trastuzumab and pertuzumab or lapatanib, albeit in a completely different manner." (PMID 27596216, 2016).
tumor (continued). "Targeted therapy of ErbB2-dependent tumours often provokes an adaptive response leading to reactivation of the PI3K/AKT pathway." (PMID 27255951, 2016). "Our studies also provide evidence that sub-therapeutic doses of an HSP90 inhibitor (1 mg/Kg 17AAG in our studies, which has little efficacy against BT-474 xenografts; unpublished data), dramatically enhances tumor killing by DOX-loaded ErbB2-targeted NGs." (PMID 26859680, 2016). "While gene amplification was found relatively constant in ERBB2-positive GC tumors, its protein expression was highly heterogeneous, often, even within the same tumor." (PMID 26955870, 2016). "In this regard, ERBB2 as well as ER/PR were shown to be differentially expressed between the primary tumor and corresponding metastases and/or CTC and the expression status was shown to change during disease progression." (PMID 27223437, 2016). "In our patient cohort, we analyzed tumor mtDNA content in relation to patient age at diagnosis, menopausal status, tumor size, histological grade, estrogen receptor status, progesterone receptor status and ERBB2 amplification." (PMID 27081694, 2016). "The chimeric antigen receptor used in our studies is comprised of T cell intracellular signaling domains, derived from CD3ζ and CD28, linked to an extracellular single chain variable fragment specific for the tumor antigen, ErbB2 (Her2)." (PMID 27153556, 2016). "CAR-based therapies have targeted antigens such as CD19, CD20, and ErbB2 that are expressed at densities that range from 10,000 to 1,000,000 molecules per tumor cell." (PMID 27703664, 2016). "Cell lines containing 17q12–22 amplification had elevated ERBB2 copy number and messenger RNA (mRNA), and were generally derived from tumours clinically annotated as having ERBB2 amplifications." (PMID 27109210, 2016). "Most IGF pathway members, including IGF1R itself, tend to be more highly expressed in luminal A and luminal B tumors and comparatively underexpressed in basal and ERBB2+ tumor types." (PMID 25964777, 2015). "The importance of these co-existing mutations has been previously discussed in the CGP report, where enhanced sensitivity to ERBB2/EGFR targeting agents appears to be related to elevated EGFR expression in tumor cells with SMAD4_MUT." (PMID 26132924, 2015). "To explore contributions of PTK6 to mammary gland tumorigenesis promoted by activated ERBB2, we crossed Ptk6−/− mice with the mouse mammary tumor virus-ERBB2 transgenic mouse line expressing activated ERBB2 and characterized tumor development and progression." (PMID 26247733, 2015). "Increased expression was observed in both Luminal B and ERBB2 expressing tumours compared to normal-like breast tissue." (PMID 26008983, 2015). "It is notable that even transgenic models of forced cyclin D1a overexpression show quite limited capacity for tumor formation, which is latent, and requires co-expression of the Erbb2 oncogene for robust tumor induction in younger mice." (PMID 25787974, 2015). "The ErbB family members: EGFR, ErbB2, ErbB3, and ErbB4 receptors are established as drivers of many aspects of tumor initiation and progression to metastasis." (PMID 25699077, 2015). "Larger acini attested to more proliferation in the ErbB2+ribose conditions, further supporting the theory of cooperation between matrix crosslinking and ErbB2 activation in driving tumour growth." (PMID 26472542, 2015). "PTK6 expression was induced in the mammary glands of ERBB2 transgenic mice before tumor development and correlated with activation of signal transducer and activator of transcription 3 (STAT3) and increased proliferation." (PMID 26247733, 2015). "When investigating differential expression of four major known oncogenes in GC, we found that MET (p = 0.00) and ERBB2 (p = 0.00) were differentially expressed between normal and tumor tissues." (PMID 26296973, 2015).
tumor (continued). "Currently, all patients are stratified to trastuzumab (or other anti-ERBB2 therapies) by primary tumor tissue analysis only." (PMID 25398926, 2015). "While 15 genes were found to be altered in two or more tumors, only 5 mutations occurred in more than one tumor model (ADCY2 p.V147L, ERBB2 p.I655V, NCF2 p.H308Q, SYNE1 p.L885V, and ZNF814 p.158V)." (PMID 26270481, 2015). "PEAK1 promotes tumor growth/metastasis and therapy resistance in human cancers via its regulation of the actin cytoskeleton and Src, KRas and ErbB2 signaling pathways." (PMID 26267863, 2015). "This receptor is a kinase dead receptor, incompetent in promoting downstream signaling, yet heterodimers of ErbB2/HER2-ErbB3/HER3 have a potent signaling competence observed in many neoplasms." (PMID 26370283, 2015). "The majority of data describing a functional role of ErbB2–ErbB3 heterodimers has been generated in mouse models of tumour progression." (PMID 26490994, 2015). "PTK6 associates with ErbB2 and promotes ErbB2-dependent Ras/MAPK signaling, suggesting PTK6 participates in tumour development." (PMID 25748447, 2015). "As assessed by WB and IHC, the receptor tyrosine kinase erbB2 was highly and similarly expressed in both tumour types." (PMID 25967547, 2015). "For example, ErbB2/ERK1, 2 signaling activates and phosphorylates the three HAS isoenzymes implicating this as a mechanism for up-regulated HA synthesis in HER2/neu-positive tumor subtypes." (PMID 26106384, 2015). "Analytical sensitivity for detection of somatic amplifications of CCNE1 and ERBB2 genes in tumour samples—concordance between ISH assay and results from the MLPA-seq." (PMID 26569395, 2015). "The tumor samples exhibiting the highest (ErbB2high, n = 10) or the lowest (ErbB2low, n = 10) mRNA level for ErbB2 were sorted (***p < 0.001)." (PMID 25890497, 2015). "Immunohistochemistry analysis of the primary tumor confirms ErbB2 positivity in all three tumors, whereas CSCs derived from the tumors stain negative." (PMID 26181203, 2015). "The roles of EMP3 in activation of PI3K by ErbB2-ErbB3 and in tumor promotion by P2X7R need to be further explored." (PMID 26472188, 2015). "The analytical sensitivity of the MLPA-seq for detection of focal amplifications was tested in 14 snap-frozen tumour or FFPE tumour samples from 12 tumours with known CCNE1 or ERBB2 amplifications, originally detected with ISH assays." (PMID 26569395, 2015). "Supportively, p95 ErbB2 forms preferentially heterodimers with ErbB3 over EGFR in BT474 tumor xenografts." (PMID 24709902, 2014). "In order to account for this, we undertook ordinal regression analyses with tumour ErbB2-IR, AR-IR and Ki67-index as the independent variables and the tumour stage as the dependent ordinal variable." (PMID 25215939, 2014). "Removal of androgens from the cell culture medium increases ErbB2 expression, and a slight increase in ErbB2 expression seven days after castration is seen in a xenograft model of tumour growth with CWR22 cells." (PMID 25215939, 2014). "Ordinal regression analyses with tumour ErbB2-IR, AR-IR and Ki67-index as the independent variables and the tumour stage as the dependent variable." (PMID 25215939, 2014). "In other words, when variables are held constant, there is an influence of the combination of ErbB2-IR x AR-IR, so that the higher the scores, the higher the tumour stage number." (PMID 25215939, 2014). "We were interested in synergistic benefits of combining erlotinib, pertuzumab or trastuzumab in ErbB-1 expressing, ErbB-2 amplified tumours with differing resistance phenotypes." (PMID 24970389, 2014).
tumor (continued). "The corresponding values for the tumour grades 1a-1b, 2, 3 and 4, respectively, were: tumour ErbB2-IR score ≤2.75, 92 [61%], 30 [20%], 25 [17%] and 3 [2%]); tumour ErbB2-IR score >2.75, 83 [41%], 61 [30%], 49 [24%] and 8 [4%] (P<0.005, χ2 test)." (PMID 25215939, 2014). "Patients with CL tumor were younger than those with luminal A, ERBB2-enriched or luminal B tumors, and older than patients with basal tumors." (PMID 25277734, 2014). "The monoclonal antibody drugs trastuzumab and pertuzumab as well as the small molecule inhibitor erlotinib were designed to prevent ErbB-2 and ErbB-1 receptor induced deregulated protein signalling, contributing to tumour progression." (PMID 24970389, 2014). "Cox proportional hazards regression analyses for tumour ErbB2-IR in cases followed by expectancy after diagnosis." (PMID 25215939, 2014). "We next sought to determine the effects of this compound on ErbB2 signaling and tumor cell viability following UVA irradiation." (PMID 24551203, 2014). "Tumor tissue samples were selected to distribute equally between the five well-established mRNA subtypes – Luminal A, Luminal B, ERBB2, Basal-like, and Normal-like - based on the PAM50 molecular classifier." (PMID 25264628, 2014). "Evaluation of a panel of anti-ERBB2 IgGs that bind the same epitope with varying affinities showed dramatic differences in tumor penetration." (PMID 25386657, 2014). "The efficient inhibition of ErbB2-induced proliferation and tumor growth was also a central qualification in the development of trastuzumab." (PMID 24709902, 2014). "Overexpression of CAM2KN1 in DU145 tumor tissues resulted in decreased ErbB2, AKT1, Bcl-2, NF-κB and AR mRNA levels and increased p21, Bax mRNA levels." (PMID 25003983, 2014). "Consistent with a central role of Plexin-B1 in ErbB-2-induced tumour progression, blockade of IKK also reduced tumour cell invasiveness." (PMID 25137062, 2014). "These include wild-type neu/ErbB2 transgenic mice with tumor latency of 30 to 52 weeks, and MMTV-cyclin D1 mice with approximately 70 weeks as mean age at onset." (PMID 25516216, 2014). "The receptor tyrosine kinases EGFR and ERBB2, the GTPases KRAS, NRAS, and HRAS, and the kinase BRAF are frequently mutated in cancers and can drive tumor proliferation." (PMID 24874471, 2014). "Increased ERBB2/3 alters multiple signaling pathways, including kinase signaling, and, thus, impairs normal cellular control mechanisms, giving rise to malignant tumor cell transformation." (PMID 24774301, 2014). "The majority of IMPC tumours were T1 (72%), grade 2 (51%) and ER-positive (100%), and ERBB2 overexpression was observed in 26% of cases." (PMID 24887297, 2014). "Conversely, treatment of female BALB/c nude mice with an ErbB2 antibody reduced tumour growth following injection of 22Rv1 Pca cells." (PMID 25215939, 2014). "This imbalance in favor of basal-like subtype is due to the low tumor take of luminal or ErbB2-positive subtypes in mouse." (PMID 25375638, 2014). "Consistent with this, Kaplan-Meier plots for all cases followed by expectancy showed a significant prognostic effect of the tumour ErbB2-IR, and for cases with Gleason scores 4–6." (PMID 25215939, 2014). "In ErbB-2-overexpressing tumour cells, such as BT-474 and MT-2, RhoA activity was strongly reduced by blockade of the IKK-complex or knockdown of Plexin-B1." (PMID 25137062, 2014). "Tumour ErbB2-IR was confirmed to be a prognostic marker for disease-specific survival, but it did not provide significant additive information to the Gleason score or to Ki-67." (PMID 25215939, 2014). "A ROC curve with a 15-year limit indicated a significant prognostic value of tumour ErbB2-IR (Area under the curve [AUC] 0.60, P<0.05), and was at the division ≤2.75 and >2.75." (PMID 25215939, 2014). "Nonetheless, the molecular basis through which tumor cells often co-express erbB2 and erbB3 remains elusive." (PMID 24886126, 2014).
tumor (continued). "Consistent with data obtained in tumour cells, Sema4D-induced ErbB-2 phosphorylation and RhoA activation in mouse osteoblasts were sensitive to the inhibition of the IKK-complex." (PMID 25137062, 2014). "ErbB-2-overexpressing tumours depend on Plexin-B1-mediated RhoA activation for tumour progression and metastasis." (PMID 25137062, 2014). "A total of 255 cases scored for tumour ErbB2-IR were followed by expectancy after diagnosis, this being the standard treatment at the time." (PMID 25215939, 2014). "While not all candidates validated by immunoblotting, we did observe phosphorylation of both ErbB2 and PDGFRβ in at least some of the recurrent tumours, suggesting that RTK signalling was actively occurring." (PMID 24457046, 2014). "This suggests robust expression of PHLDA1 in mammary epithelium, downregulation of PHLDA1 in tumor versus adjacent normal tissue suggestive of a putative tumor suppressor role and also regulation by ErbB2 as suggested by the profiling studies as well." (PMID 25238247, 2014). "In this context, ErbB2 targeted therapies have previously been shown to sensitize tumor cells to radiation therapy." (PMID 24551203, 2014). "Further, in a xenograft model using castrated mice, the ErbB2-expressing cells produced a more rapid tumour formation than the untransfected LNCaP cells." (PMID 25215939, 2014). "Although there is some clinical evidence to support these preclinical findings, only 10% of ER+ tumours coexpress ERBB2, and ERBB2 is rarely overexpressed with acquisition of resistance." (PMID 25358600, 2014). "In principle, expression of ErbB2 in breast CSCs suggests that ErbB2-targeted anti-cancer therapies would be efficient also against the tumor initiating CSC." (PMID 24709902, 2014). "In only 1 out of 6 patients, CTCs shared the mutational state of the oncogenes ERBB2 and PIK3CA with the primary tumor." (PMID 25358515, 2014). "No statistical difference was found between the diversin overexpression and age (p = 0.9263), tumor size (p = 0.2371), ErbB2 status (p = 0.4613) and progesterone receptor status (p = 0.1054)." (PMID 24858714, 2014). "In order to investigate this possibility, two approaches have been taken, using the tumour ErbB2-IR together with three other tumour markers (Ki67 index, epithelial AR-IR and pAkt)." (PMID 25215939, 2014). "With intact ErbB2, attenuated TGFβ signaling has the opposite effect in spite of the fact that tumor latency increases." (PMID 25280532, 2014). "Conversely, the cluster related to the luminal progenitor cells is predominated by gene signatures of highly proliferative tumours (Luminal B, Basal-like and ErbB2+) and includes the poor prognosis signatures (IGS, 70GENE, WHR, ROR_S and ROR_P)." (PMID 24586640, 2014). "Comparable levels of IFN-γ were secreted by both CARs in response to incubation with erbB2+ tumor cells." (PMID 23667569, 2013). "It indicates that the inhibitory effect of EC1-GLuc-p53C on the tumor growth has an ErbB2-targeting property and is derived from the efficacy of p53C peptide in the fusion protein, which is similar to those in vitro." (PMID 24069396, 2013). "While the role of ErbB2 in tumor cell proliferation and survival has been largely studied, less is known about the possible contribution of ErbB2 to tumor cell motility, invasion and metastasis." (PMID 23383112, 2013). "In tumor cells, ErbB2 activates ErbB3, which stimulates several intracellular signaling proteins and pathways, including MAPK, PI3K/Akt and Src kinase." (PMID 23739740, 2013). "Bim-deficient tumors grew slower than the wild-type tumors, suggesting that BIM plays a role in ErbB2-mediated tumor growth." (PMID 23577147, 2013). "Despite the plethora of ERBB2 targeted compounds, we currently lack a sound understanding why tumor shrinkage is short-lived and only a relatively small percentage of patients benefit from these therapies." (PMID 23630663, 2013).